AKT2 (AKT serine/threonine kinase 2)
Diseases named in the same sentence as AKT2 in open-access papers (continued):
Sharing a sentence is not in itself a finding about the gene and the disease.
gastric tumours (2 papers, 2013 to 2022). "Gene expression analysis of gastric tumour samples from The Cancer Genome Atlas (TCGA) stomach adenocarcinoma (STAD) cohort revealed that the expression of the AKT3 isoform (but not AKT1 or AKT2) is inversely correlated to the expression of CDH1 in gastric tumours." (PMID 35406381, 2022).
Glomerular sclerosis (2 papers, 2018 to 2020). Accumulation of scar tissue within the glomerulus. "It has been reported that deletion of the Akt2 gene causes loss of the normal skeletal structure of glomerular podocytes, leading to the apoptosis and fusion of podocytes, which results in severe proteinuria and glomerular sclerosis." (PMID 32025205, 2020). "Akt2 controls podocyte hypertrophy and matrix protein expression via deptor: Podocyte hypertrophy and matrix protein synthesis contribute to glomerulosclerosis in various kidney diseases." (PMID 30444896, 2018). "In summary, our results provide the first mechanistic view for involvement of Akt2 in TGFβ stimulated podocyte hypertrophy and matrix protein accumulation seen in glomerulosclerosis." (PMID 30444896, 2018). "Furthermore, we provide the first evidence that deptor downstream of Akt2 contributes to podocyte hypertrophy and matrix protein expression found in glomerulosclerosis in different renal diseases." (PMID 30444896, 2018).
hyperandrogenemia (2 papers, 2021 to 2023). "Moreover, gene polymorphisms in AKT1 and AKT2 were associated with T2D, polycystic ovarian syndrome (PCOS) and cancer in the Chinese population." (PMID 37754255, 2023). "There is a positive correlation between the expression levels of AKT1 and AKT2 with androgens, and high expressions of AKT1 and AKT2 may cause GCs dysfunction in the PCOS patients with hyperandrogenemia and may lead to PCOS." (PMID 34306142, 2021).
hypertriglyceridemia (2 papers, 2017 to 2023). A laboratory test result indicating elevated triglyceride concentration in the blood. "Moreover, this association between high SUA and hypertriglyceridemia could be explained to some extent by alterations in the metabolism of lipids, especially triglycerides, through the activation of mitochondrial NADPH oxidase and inhibition of AMPK and AKT2." (PMID 37537612, 2023).
Hypoinsulinemia (2 papers, 2019 to 2021). A decreased concentration of insulin in the blood. "Conversely, the activating mutation AKT2-Glu17Lys within the PH domain of AKT2, required for docking to PIP3 at the plasma membrane, results in hypoinsulinemia." (PMID 33893069, 2021).
infertile (2 papers, 2016 to 2021). "A recent study demonstrated abnormal Akt signaling in infertile women with non-cavity-distorting intramural UFs; these women exhibited higher expressions of Akt1, Akt2, p-Akt, and phospho-PTEN and a lower expression of PTEN mRNA in the endometrium compared to fertile women." (PMID 34113609, 2021).
inflammatory bowel disease (2 papers, 2019 to 2024). A spectrum of small and large bowel inflammatory diseases of unknown etiology. "miR-150, which is associated with inflammatory bowel disease (IBD) and pain, is upregulated and interacts with protein kinase (AKT2), which may affect inflammatory pathways." (PMID 38967892, 2024).
insulin resistant diabetes (2 papers, 2021 to 2023). "Therefore, PP1γ act like a possible linker between two disorders, insulin resistant diabetes and AD through AKT2 and MLK3, generating a possibility leading to Type-3 diabetes." (PMID 37085815, 2023).
ischemia (2 papers, 2017 to 2021). A hypoperfusion of the BLOOD through an organ or tissue caused by a PATHOLOGIC CONSTRICTION or obstruction of its BLOOD VESSELS, or an absence of BLOOD CIRCULATION. "However, the function of AKT2 deficiency on cardiac ischemia/reperfusion (I/R) injury is controversial, with most reports suggesting AKT2−/− cardiomyocytes were sensitized to apoptosis, and one supporting a beneficial effect during cardiac I/R." (PMID 28272306, 2017). "In our research, we found that the role of extrinsic apoptosis pathway is inactivated due to the sustained low caspase-8 activity in AKT2-inhibited cardiomyocytes during ischemia." (PMID 28272306, 2017). "The current study is the first that elucidates the function and mechanism of AKT2 in cardiac apoptosis during ischemia." (PMID 28272306, 2017). "Taken together, our results above indicate that AKT2 inhibition induces the silencing of caspase-dependent apoptosis of the internal signaling pathway in cardiomyocytes during ischemia and hence prompts a distinct cell death signaling pathway that could be provoked by AKT2 inhibition." (PMID 28272306, 2017). "The decrease of caspase-9 and -3 activity was significant between cardiomyocytes treated with and without zVAD during ischemia, while there were no obvious changes when AKT2 was inhibited." (PMID 28272306, 2017).
lupus (2 papers, 2021). "Similar to our previous findings in the MRL/lpr cortex, Akt2 appears to play a central role in the TWEAK/Fn14-induced effects of the hippocampus of the lupus model." (PMID 34440346, 2021). "Our analysis highlights the importance of Akt2 in particular, and the PI3K-AKT pathway in general, in the genomic regulation of the MRL/lpr lupus-prone mouse." (PMID 34440346, 2021). "The lack of correlation of Akt2 with Tnfrsf12a in the lupus mouse model may be due to a discrepancy between Tnfrsf12a gene expression (quantified here) and its activation." (PMID 34440346, 2021).
lymphoma (2 papers, 2018 to 2024). A malignant (clonal) proliferation of B- lymphocytes or T- lymphocytes which involves the lymph nodes, bone marrow and/or extranodal sites. "The PI3K signaling pathway is usually activated in lymphoma, and inactivation of this pathway impairs DNA repair following radiation, then, we found that levels of both AKT2 and AKT3 were reduced in all miR-150 transductants." (PMID 29386059, 2018).
megalencephalies (2 papers, 2017 to 2021). "Three patients with megalencephaly, diffuse asymmetric overgrowth, hypoketotic, hypoinsulinaemic hypoglycaemia and no AKT2 mutation underwent further genetic, clinical and metabolic investigation." (PMID 28566443, 2017).
Merkel cell carcinoma (2 papers, 2016 to 2024). "Firstly, we compared the gene expression of AKT2 and DAPK1 in pan-cancer, among which Merkel cell carcinoma and Skin cutaneous melanoma (SKCM) ranked the highest AKT2 and DAPK1 expression, respectively." (PMID 38310291, 2024). "Importantly, aberrations in the PI3K/AKT/mTOR pathway (AKT2, FBXW7, NF1, PIK3CA, PIK3R1, PTEN or RICTOR) were also commonly seen in Merkel cell carcinomas (9/17 [53%])." (PMID 26981779, 2016).
myopia (2 papers, 2007 to 2025). "Conversely, activation of the PI3K/AKT signaling pathway will be inhibited under strong stress (stress lasting for 4-week myopia induction), which leads to the decreased expression of p-AKT2 and enhances BAD level, thereby initiating apoptotic signaling and causing apoptosis." (PMID 40216914, 2025). "Akt2 therefore may be a new and interesting candidate for involvement in signal transduction during myopia development." (PMID 17653032, 2007). "Meanwhile, the Gene Ontology (GO) functional annotation analysis showed that differentially expressed genes (such as PIK3R3 and AKT2) could play a role in the occurrence and development of myopia by affecting cell survival and function as well as cell migration." (PMID 40216914, 2025). "In the present study, we noted that under mild stress (stress lasting for 2-week myopia induction), activated PI3K/AKT signaling pathway promotes the expression of p-AKT2 and BCL-2, which can inhibit apoptotic signaling and contribute to cell survival." (PMID 40216914, 2025). "After myopia induction for 2 and 4 weeks, the expression of PIK3R3, AKT2, BAD, BCL-2, TGF-β1, E-cadherin, COLI, MMP2, and TIMP2 was detected by qPCR." (PMID 40216914, 2025). "Further, we investigated the changes of PIK3R3, AKT2 and TGF-β1, E-cadherin, COLI, BCL-2, BAD, MMP2, and TIMP2 in the sclera of myopic guinea pigs to explore their effects on the development of myopia after 2- and 4-week myopic induction." (PMID 40216914, 2025). "In contrast, the expression trend of the related molecules was reversed after 4 weeks of myopia induction (*P < 0.05, **P < 0.01, and ****P < 0.0001), suggesting that PIK3R3 and p-AKT2 may be correlated with cell survival and apoptosis." (PMID 40216914, 2025).
Nephropathy (2 papers, 2020 to 2025). A nonspecific term referring to disease or damage of the kidneys. "Cluster 3 (n = 95) comprised patients with low miR-375 expression and low IRS1 and AKT2 activity, poor glucose control, and the lowest adherence, as well as the most cardiovascular disease and nephropathy." (PMID 40786421, 2025).
overnutrition (2 papers, 2015 to 2017). An imbalanced nutritional status resulting from excessive intake of nutrients. "Intriguingly, HO-1 & Akt2 may befunctionally linked as modulation of both, HO-1 and Akt2 signaling affects adipose precursor proliferation in the setting of overnutrition, yet dispensable for normal development of WAT." (PMID 28102348, 2017).
Parkinson disease (2 papers, 2013 to 2025). A progressive degenerative disorder of the central nervous system characterized by loss of dopamine producing neurons in the substantia nigra and the presence of Lewy bodies in the substantia nigra and locus coeruleus. "The next topic to research will be the BDNF/CREB and PI3K/AKT modulation effects of PF’s protection against Parkinson’s disease, and, in particular, the determination of the expression levels of proteins such as AKT, P-PI3K, and AKT2." (PMID 40650274, 2025).
prostate adenocarcinoma (2 papers, 2023 to 2024). "Of the four PDK isoforms (PDHK1-4), PDHK1 is the most frequently studied in the context of tumorigenesis and has previously been shown to be a direct target of AKT2 in prostate adenocarcinoma cells." (PMID 37894325, 2023). "In addition, the knockdown of AKT1 and AKT2 reduced lactate production in the prostatic adenocarcinoma cell line PC3." (PMID 38396845, 2024).
prostate tumors (2 papers, 2021 to 2023). "Previous work in PTEN-deficient prostate tumors demonstrated their dependence on AKT2 for both maintenance and survival, but AKT1 in the same tumors was dispensable." (PMID 37894325, 2023). "A low dose of Akt1 or Akt2 inhibitor enabled standard chemotherapies to significantly eradicate metastatic prostate tumors in a mouse model, acting as chemosensitizers." (PMID 34591413, 2021).
rhabdomyosarcoma (2 papers, 2022 to 2024). A rare aggressive malignant mesenchymal neoplasm arising from skeletal muscle. "This included a solid pseudopapillary neoplasm of pancreas (everolimus for high Ras homolog enriched in brain (RHEB)), EPN (bevacizumab for high VEGFA) and rhabdomyosarcoma (temsirolimus/vinorelbine/cyclophosphamide for high AKT2)." (PMID 38844796, 2024).
rheumatoid arthritis (2 papers, 2021 to 2022). A chronic, systemic autoimmune disorder characterized by inflammation in the synovial membranes and articular surfaces. "In RASFs from 16 patients with rheumatoid arthritis (RA) and 13 patients with joint trauma who underwent joint replacement surgery, miR-650 was down-regulated, whereas AKT2 was up-regulated." (PMID 35401513, 2022). "Hsa-miR-650 was reported to suppress proliferation, migration and invasion in individuals with rheumatoid arthritis by targeting AKT2." (PMID 34804121, 2021). "In some reports, hsa-miR-650 targets AKT serine/threonine kinase 2 (AKT2) and inhibits the proliferation, migration and invasion of synovial fibroblasts in individuals with rheumatoid arthritis." (PMID 34804121, 2021).
sarcoma (2 papers, 2020 to 2021). A usually aggressive malignant neoplasm of the soft tissue or bone. "This may point to the evolution of a high-grade sarcoma from a H3F3A-negative, but FGFR1-positive subclone with acquisition of additional mutations in AKT2 and NRAS during tumor progression." (PMID 33707617, 2021). "In addition, we detected a mutation in AKT2 and NRAS in the sarcoma." (PMID 33707617, 2021).
serous adenocarcinoma (2 papers, 2013 to 2025). An adenocarcinoma that is characterized by the presence of papillary patterns and cellular budding. "An exclusive MDM2 amplification was identified within the serous adenocarcinoma fraction, while an ARID2 loss and an AKT2 amplification were uniquely present in the SC-NEC compartment." (PMID 40833530, 2025).
T-cell leukemia (2 papers, 2018 to 2021). A malignant disease of the T-lymphocytes in the bone marrow, thymus, and/or blood. "To assess whether miR-126-3p was able to regulate these putative target genes, we transfected the T-cell leukemia cell line Jurkat with a miR-126-3p mimic and we evaluated the impact of its ectopic expression on AKT2, PPP3CB, RANKL, and SDC2 transcript levels." (PMID 29850558, 2018).
thymic lymphomas (2 papers, 2016 to 2025). "Thus, AktT mice, in which a constitutively active Akt2 is expressed in immature T cells, develop spontaneous thymic lymphomas, which cannot be prevented in rpS6P-/-;Akttg MEFs double mutant mice." (PMID 26919188, 2016).
acute promyelocytic leukemia (1 paper, 2024). An aggressive form of acute myeloid leukemia (AML), characterized by arrest of leukocyte differentiation at the promyelocyte stage, due to a specific chromosomal translocation t(15;17) in myeloid cells. "The M3 group, also called “acute promyelocytic leukemia”, and which represents a separate entity characterized by the PML-RARA chromosomal translocation, shows a homogenous pattern of AKT3 expression, and a significant ~ twofold increase in AKT2 expression." (PMID 38528080, 2024).
adenosarcoma (1 paper, 2017). A low grade malignant neoplasm characterized by the presence of a benign epithelial component (tubular and cleft-like glands) and a low grade sarcomatous component that contains varying amounts of fibrous and smooth muscle tissues. "In our cohort of adenosarcomas, we detected alterations in PI3K pathway in 26% (5/19) of cases (PIK3CA, PIK3CG, PIK3R1, PTEN mutations and/or amplification of AKT2 or ERBB3)." (PMID 28267263, 2017).
anaplastic glioma (1 paper, 2019). "The stable knockdown of circ-AKT3 in SW1783 cells and in Hs683 anaplastic glioma cells only reduced AKT3-174aa expression, instead of reducing that of AKT1, AKT2 and AKT3." (PMID 31470874, 2019).
Ataxia (1 paper, 2020). Ataxia refers to impaired coordination of voluntary muscle movement. "More specifically, the PIK3R1 gene was under-expressed in neuronal datasets as well as in fibroblasts and peripheral blood, while AKT2, PPP2R5C, and SPTLC1 were found over-expressed in neuronal and fibroblast datasets of the “ataxia” phenotype." (PMID 32937819, 2020).
B-cell CLL (1 paper, 2016). "Similarly, activation of serine/threonine-protein kinases (Akt2 and Akt3) in combination with B-cell CLL/lymphoma (Bcl2), collagen (COL4A1), Src transforming protein (SHC1) lead to the activation of focal adhesion pathway." (PMID 27367858, 2016).
Burkitt lymphoma (1 paper, 2019). A rare form of malignant mature B-cell non-Hodgkin lymphoma. "Flow cytometry experiments demonstrate inhibition of Akt1 or Akt2 in CCRF-CEM, CEM-DR, Jurkat, and highly GC-resistant Burkitt’s lymphoma cell line Daudi with a concentration of 0.8 μM Akt isoform inhibitors effectively restores GC-induced apoptosis." (PMID 30598523, 2019).
cervical (1 paper, 2020). "Increased AKT2 expression was associated with the cervical lesion progression." (PMID 33123457, 2020).
chronic kidney disease (1 paper, 2023). Impairment of the renal function secondary to chronic kidney damage persisting for three or more months. "AKT2 signaling is renoprotective in T1D by enhancing antioxidant signaling with AMPK activation and promotes podocyte viability in chronic kidney disease." (PMID 37791586, 2023).
clear cell adenocarcinoma (1 paper, 2013). A malignant neoplasm composed of glandular epithelial clear cells. "Although previously reported in ovarian serous neoplasms, our study is the first to report AKT2 amplification in clear cell adenocarcinoma." (PMID 23469222, 2013).
diabetic eye disease (1 paper, 2023). A group of disorders affecting the eye in patients with diabetes mellitus. "Collectively, our results demonstrate complex Akt2 signaling in the RPE during the progression of DR and identify a pathway (Akt2/ERK) that could be manipulated to develop new therapies for the treatment of diabetic eye disease." (PMID 37443129, 2023).
endothelial dysfunction (1 paper, 2019). In vascular diseases, endothelial dysfunction is a systemic pathological state of the endothelium (the inner lining of blood vessels) and can be broadly defined as an imbalance between vasodilating and vasoconstricting substances produced by (or acting on) the endothelium. "Our study aimed to understand endothelial dysfunction by taking advantage of our previously established protocol for generating ECs from PSCs and genome editing to create models of rare metabolic diseases with AKT2 dysregulation in vitro." (PMID 31835296, 2019).
ependymoma (1 paper, 2017). A WHO grade II, slow growing tumor of children and young adults, usually located intraventricularly. "A recent study also demonstrated that the putative ependymoma oncogene AKT2 could drive formation of ependymomas in mice." (PMID 27926496, 2017). "However, gain of AKT2 has only been detected in approximately 4% of ependymomas." (PMID 27926496, 2017).
fallopian tube carcinoma (1 paper, 2024). A carcinoma that arises from epithelial cells of the fallopian tube. "A report at the 2016 ASCO meeting showed a cohort of 379 patients with ovarian or fallopian tube carcinoma have been evaluated for 10 genes AKT1, AKT2, AKT3, mTOR, PIK3CA, PIK3C2B, PIK3R1, PTEN, TSC1, TSC2 in the PI3K/AKT/mTOR pathway." (PMID 38167649, 2024).
gout (1 paper, 2019). A condition characterized by painful swelling of the joints, which is caused by deposition of urate crystals. "Further support for the role of the ILS pathway in modulating UA metabolism stems from a human candidate gene study identifying SNPs in the ILS genes AKT2 and FOXO3 being associated with serum UA levels or gout." (PMID 31415568, 2019).
hepatic (1 paper, 2022). "Exenatide may improve adipose tissue-associated hepatic IR by inhibiting adipokines and regulating the expression of key proteins in the IRS2/PI3K/Akt2 pathway." (PMID 36246878, 2022).
hyperlipidemia (1 paper, 2022). "This study showed that hyperlipidemia selectively activates Akt2 in Tregs and that Akt2 activation promotes glycolysis and the secretion of proinflammatory cytokines." (PMID 36081513, 2022). "Therefore, selective activation of Akt2 by hyperlipidemia promotes inflammation by functionally reprogramming the Tregs." (PMID 36081513, 2022).
infarction (1 paper, 2017). A localised pathological necrosis of tissue resulting from obstruction of the blood supply usually by a thrombus, an embolus, or vascular torsion. "Atorvastatin attenuated post-ischemic pathologic remodeling by suppressing the levels of phosphorylated AKT2, NBA1, and phosphorylated SPK1, macrophage recruitment, apoptosis, collagen deposition, and increased angiogenesis in the infarction area." (PMID 29383164, 2017). "AKT2 phosphorylation, NBA1, SPK1, SPK1 phosphorylation, F4/80 protein expression, F4/80 density, and hypertrophy marker ANP mRNA expression in the infarction area were promoted at day 7 after MI without treatment and diminished by atorvastatin treatment." (PMID 29383164, 2017).